PIM2 (Pim-2 proto-oncogene, serine/threonine kinase)
Diseases named in the same sentence as PIM2 in open-access papers (continued):
Sharing a sentence is not in itself a finding about the gene and the disease.
mantle cell lymphoma (4 papers, 2014 to 2018). Mantle cell lymphoma is a rare form of malignant non-Hodgkin lymphoma affecting B lymphocytes in the lymph nodes in a region called the ``mantle zone''. "Increased levels of Pim-2 were also found in mantle cell lymphoma (MCL), follicular lymphoma (FL), marginal zone lymphoma-MALT type (MZL-MALT), chronic lymphocytic leukemia (CLL), nodal marginal zone lymphoma (NMZL) and multiple myeloma." (PMID 25491234, 2014).
non-Hodgkin lymphoma (4 papers, 2012 to 2022). Distinct from Hodgkin lymphoma both morphologically and biologically, non-Hodgkin lymphoma (NHL) is characterized by the absence of Reed-Sternberg cells, can occur at any age, and usually presents as a localized or generalized lymphadenopathy associated with fever and weight loss. "For example, in Non-Hodgkin Lymphoma (NHL) and in Chronic Lymphocytic Leukemia (CLL), significant up-regulation of PIM-2 was observed." (PMID 22506047, 2012).
T cell lymphomas (4 papers, 2012 to 2023). "Transgenic mice over-expressing PIM2 are predisposed to T cell lymphomas, whereas PIM2 acts synergistically with c-Myc to accelerate development of B-cell tumors." (PMID 24505470, 2014). "In this mouse model, the overexpression of a pim2 transgene in lymphoid cells predisposed mice to T-cell lymphomas that were similar to those promoted by pim1 transgenes." (PMID 24860787, 2014). "Transgenic mice over-expressing either Pim-1 or Pim-2 are predisposed to T cell lymphomas, whereas both Pim-1 and Pim-2 act synergistically with c-Myc to accelerate development of B-cell tumors." (PMID 22506047, 2012). "Pim1 was discovered as a proviral insertion site in Moloney-murine leukemia virus in T-cell lymphomas, and further studies identified the other two family members, pim2 and pim3, as alternative integration sites." (PMID 24860787, 2014).
colon cancer (3 papers, 2015 to 2019). "When PIM1 was inhibited, PIM2 expression increased across different cancer types generally, and Pim-3 was reported to be aberrantly expressed in colon cancer." (PMID 25749522, 2015). "PIM2 inhibitor also inhibited HK2 Thr473 phosphorylation in SW480 colon cancer cells." (PMID 29985480, 2018). "In this study, we demonstrated that siphonodictyal B inhibits several kinases such as CDK4/6, CDK7, and PIM2 in addition to PI3K in vitro and that siphonodictyal B exhibits more potent cytotoxic effects than liphagal against human colon cancer cell lines." (PMID 31364822, 2019).
rheumatoid arthritis (3 papers, 2015 to 2025). A chronic, systemic autoimmune disorder characterized by inflammation in the synovial membranes and articular surfaces. "Previous reports have suggested that Pim-2 protein expression is increased in 4-HNE-induced intrinsic inflammation within human rheumatoid arthritis synovial cells." (PMID 34547720, 2021).
asthma (2 papers, 2018 to 2021). "Pim-2 slows down the development of asthma by inhibiting the secretion of inflammatory factors in Tregs." (PMID 34547720, 2021). "Most importantly, the mRNA levels of USP21 and PIM2 were upregulated in the Treg cells of asthma patients." (PMID 30013989, 2018). "Previous studies showed that both USP21 and PIM2 are regulators of GATA3 and FOXP3 expression, respectively, in Treg cells, so we measured the expressions of USP21 and PIM2 in Treg cells from patients with asthma and healthy subjects." (PMID 30013989, 2018). "We thought the explanation was that USP21 or PIM2 may regulate the expression in a complicated way rather than in a linear relationship and it is possible that other molecules participate in the regulation of Treg cells in the pathogen of asthma." (PMID 30013989, 2018).
atherosclerosis (2 papers, 2021 to 2024). A disease characterized by the build-up of fatty material and calcium deposition in the arterial wall resulting in partial or complete occlusion of the arterial lumen. "Specifically, this function of PIM-2 has been found in RA in the case of oxidative stress caused by lipid peroxidation and in atherosclerosis, a condition in which PIM-2 plays a protective role against inflammation." (PMID 38542097, 2024). "Our current data cannot exclude the role of Pim-2 in other cell types, such as vessel endothelial cells and smooth muscle cells in atherosclerosis progression." (PMID 34547720, 2021). "Therefore, 24 h was selected as a suitable time point to investigate the role of Pim-2 and mTOR signaling pathways in atherosclerosis in subsequent experiments." (PMID 34547720, 2021). "Our findings offer novel insight that Pim-2 may serve as a therapeutic target in atherosclerosis." (PMID 34547720, 2021). "Considering that the exact role of Pim-2 in atherosclerosis remains unknown, we investigated whether Pim-2 kinase inhibits atherosclerotic inflammation by suppressing the mTORC1 pathway in ox-LDL-treated THP-1-derived macrophages and ApoE -/- mice fed a high-fat diet." (PMID 34547720, 2021).
chronic myeloid leukemia (2 papers, 2023 to 2025). "Pim2 is a pro-survival kinase which has been postulated as a therapeutic target for eradication of chronic myeloid leukemia stem cells." (PMID 40868343, 2025). "Our data showing significant increase in STAT4 is consistent with a previous report that STAT4 signaling pathways regulated the process of PIM2-phosphorylation of BAD in chronic myeloid leukemia (CML)." (PMID 38023123, 2023).
colorectal cancer (2 papers, 2014 to 2022). A primary or metastatic malignant neoplasm that affects the colon or rectum. "Pim-2 activates glucose utilization and aerobic glycolysis in colorectal cancer cells and increases energy production." (PMID 36612063, 2022).
coronary artery disease (2 papers, 2021 to 2023). "Pim-1 is increased 11-fold in coronary artery disease, present in pulmonary arterial hypertension, and Pim-2 is upregulated in atherosclerotic arteries in coronary artery disease." (PMID 37511341, 2023). "We found that the protein expression of Pim-2 is upregulated in ox-LDL-treated THP-1-derived macrophages and an atherosclerotic mouse model, finding that is consistent with clinical phenomenology that Pim-2 is upregulated in atherosclerotic arteries in coronary artery disease patients." (PMID 34547720, 2021).
melanoma (2 papers, 2016 to 2026). A malignant, usually aggressive tumor composed of atypical, neoplastic melanocytes. "The immunosuppressive role of PIM2 was validated in human T cells, where inhibition of PIM2 enhanced antitumor responses in engineered human T cells, including melanoma-specific TCR T cells and CD19 CAR T cells." (PMID 41592107, 2026). "We observed the expression of PIM1 and PIM2 in all melanoma samples, while PIM2 and PIM3 levels were most elevated in samples expressing lower PIM1 levels." (PMID 27448973, 2016). "Using knockdown studies, we showed that PIM1 contributes to melanoma cell proliferation and tumor growth in vivo; however, the presence of PIM2 and PIM3 could also influence the outcome." (PMID 27448973, 2016). "To confirm PIM kinases as valid targets for melanoma patients and to assess expression variability, we stained human melanoma tissue for PIM1, PIM2, PIM3." (PMID 27448973, 2016).
myeloid leukemia (2 papers, 2014 to 2015). A clonal proliferation of myeloid cells and their precursors in the bone marrow, peripheral blood, and spleen. "Transplantation of murine bone marrow co-expressing MYC and PIM1, PIM2 or PIM3 caused rapid and uniformly lethal myeloid leukemia." (PMID 25238262, 2014). "Another PIM2/MYC mouse (mouse #8) showed myeloid leukemia phenotype as judged by FACS analysis, and we were able to establish an in vitro cell line of myeloid phenotype (Gr-1+, Mac-1+, B220-)." (PMID 26606454, 2015).
osteoarthritis (2 papers, 2024 to 2025). A noninflammatory degenerative joint disease occurring chiefly in older persons, characterized by degeneration of the articular cartilage, hypertrophy of bone at the margins and changes in the synovial membrane. "Abrine has the highest affinity for the CASP8 docking pocket and has been shown to inhibit apoptosis of osteoblasts in osteoarthritis through the PIM2/VEGF signaling pathway." (PMID 38439022, 2024).
osteosarcoma (2 papers, 2012 to 2022). A usually aggressive malignant bone-forming mesenchymal neoplasm, predominantly affecting adolescents and young adults. "Narlik-Grassow further explored the impact of the other two PIM kinase family members in osteosarcoma using mouse embryonic fibroblasts (MEFs) generated from PIM2/3 knockout and PIM triple knockout (TKO) mice." (PMID 35892829, 2022). "Narlik-Grassow similarly found that PIM1, but not PIM2 or PIM3, expression correlated with poorer prognosis in osteosarcoma." (PMID 35892829, 2022).
pancreatic cancer (2 papers, 2015 to 2024). "Furthermore, we previously showed that human pancreatic cancer cells express much lower levels of Pim-1 and Pim-2 mRNA than Pim-3 mRNA." (PMID 25971209, 2015). "Additionally, in prostate cancer (DU45) and pancreatic cancer (MiaPaCa-2) cell lines, PIM3 specifically, but not PIM1 and PIM2, regulates p-STAT3 levels, potentially through its protein tyrosine phosphatase and tyrosine kinase activity." (PMID 38339286, 2024).
prostate tumors (2 papers, 2016 to 2021). "We also found that PIM1 and PIM2 are overexpressed in a subset of human male germ cell and prostate tumors and that this overexpression correlated with clear inflammatory features and stem cell markers." (PMID 27901106, 2016). "We also found that PIM1 and PIM2 are overexpressed in a subset of male germ cell and prostate tumors and that this overexpression correlated with clear inflammatory features and stem cell markers." (PMID 27901106, 2016). "Furthermore, Pim-2 was overexpressed in a subset of human male germ cells and prostate tumors, correlating with the inflammatory response." (PMID 34547720, 2021). "Therefore, we tested whether PIM1 and PIM2 expression is correlated with stem markers in human male germ cell and prostate tumors." (PMID 27901106, 2016).
sarcoma (2 papers, 2014 to 2023). A usually aggressive malignant neoplasm of the soft tissue or bone. "We showed that the absence of Pim2 and Pim3 greatly reduced sarcoma growth and that the extent of this reduction was similar to that observed in the absence of all three isoforms." (PMID 24860787, 2014).
acute leukemia (1 paper, 2010). A clonal (malignant) hematopoietic disorder with an acute onset, affecting the bone marrow and the peripheral blood. "Finally, the oncogene PIM2, which is dysregulated in acute leukemia, has recently been shown to be up-regulated in a microarray screen using post-mortem brain-derived microglia." (PMID 20515496, 2010).
adenosquamous carcinoma (1 paper, 2017). A carcinoma composed of malignant glandular cells and malignant squamous cells. "On the other hand, approximately 15% of PIM2 transgenic females harbored tumors, all of which were adenosquamous carcinoma." (PMID 28938604, 2017).
Arthritis (1 paper, 2025). Inflammation of a joint. "Pim2 was found to be more highly expressed in patients with RA than in patients with other types of arthritis." (PMID 40000906, 2025). "Conditional knockout of Pim2 in macrophages or administration of the Pim2 inhibitor HJ-PI01 attenuated arthritis development by inhibiting M1 macrophage polarization." (PMID 40000906, 2025). "To explore the role of Pim2 in inflammatory arthritis, we generated macrophage-specific Pim2 knockout mice (Pim2fl/fl-Lyz2Cre mice) and their littermate controls (Pim2fl/fl mice) and subjected them to arthritis induction." (PMID 40000906, 2025).
Burkitt lymphoma (1 paper, 2015). A rare form of malignant mature B-cell non-Hodgkin lymphoma. "In contrast, PIM2 knockdown significantly reduced Raji cell number, suggesting that PIM2 might have an important function in maintaining Burkitt lymphoma cell growth." (PMID 26643319, 2015).
cardiomyopathy (1 paper, 2023). A disease of the heart muscle or myocardium proper. "This suggests potential redundancy between the isoforms, with Pim-2 and -3 compensating for the loss of Pim-1 in basal conditions to prevent cardiomyopathy, with loss of cardiac Pim-1 associated with increased expression of Pim-2." (PMID 37511341, 2023).
Cirrhosis (1 paper, 2020). A chronic disorder of the liver in which liver tissue becomes scarred and is partially replaced by regenerative nodules and fibrotic tissue resulting in loss of liver function. "And we further divided cirrhotic HCC patients into mild, moderate, and severe group according to the severity of cirrhosis, and found that the average ΔCt value of PIM2 was gradually decreased as the severity of cirrhosis increased." (PMID 32641749, 2020). "This indicates that the feedback loop between PIM2 and TNFα maybe a driven force between chronic liver inflammation and cirrhosis." (PMID 32641749, 2020).
colorectal tumor (1 paper, 2021). "PIM2 is known to regulate glucose metabolism in cancer cells, and PIM2-mediated aerobic glycolysis has been shown to be crucial for colorectal tumor cells in concert with mTORC1 signaling." (PMID 33854618, 2021).
congenital heart disease (1 paper, 2014). A heart disease that is present at birth. "Age, PIM2, meningitis/meningoencephalitis, multiple organ dysfunction syndrome, congenital heart disease, following PALS/GEM guidelines, and shock are significantly associated with mortality." (PMID 24868211, 2014).
endometriosis (1 paper, 2022). The growth of functional endometrial tissue in anatomic sites outside the uterine body. "To further determine that PIM2 can regulate PFKFB4 in vivo, we utilized PIM2-knockout endometrial tissue as a donor to construct a mouse model of endometriosis." (PMID 36109523, 2022). "Here we tested the glucose consumption and lactate production after changing PIM2 expression in endometriosis cells." (PMID 36109523, 2022). "The findings show that PIM2 expression was positively correlated with PFKFB4 in endometriosis in vivo." (PMID 36109523, 2022). "Simultaneously, PFKFB4 expression was decreased when PIM2 expression was knocked down by shPIM2 in endometriosis cells." (PMID 36109523, 2022). "Interestingly, when we knocked down PFKFB4 in endometriosis cells by shPFKFB4 and then overexpressed PIM2 protein levels, the glucose consumption, and lactate production were not clearly changed." (PMID 36109523, 2022). "Moreover, PIM2 expression was really corresponding prevalent with PFKFB4 in endometriosis in vivo." (PMID 36109523, 2022). "Moreover, PIM2 expression is positively correlated with PFKFB4 in endometriosis in vivo." (PMID 36109523, 2022). "Then, we analyzed the change regions between PIM2 and PFKFB4 in endometriosis cells by confocal analysis and found that PFKFB4 protein level expression was decreased when shPIM2 was used to knock down PIM2 expression." (PMID 36109523, 2022). "Therefore, PIM2 and PFKFB4 Thr140 phosphorylation promotes glycolysis in endometriosis." (PMID 36109523, 2022).
fibrolamellar carcinoma (1 paper, 2023). "(H) Schematic of DNAJ-PKAc mediating cell proliferation in fibrolamellar carcinoma (FLC) by increasing c-MYC expression by increased translation, with additional effects via GSK3B, AURKA, and PIM2." (PMID 36692000, 2023).
fluid overload (1 paper, 2016). "Patients with a high PIM2 score were prone to have early fluid overload in our study." (PMID 27467522, 2016).
follicular carcinoma (1 paper, 2021).
Granuloma (1 paper, 2009). A compact, organized collection of mature mononuclear phagocytes, which may be but is not necessarily accompanied by accessory features such as necrosis. "In addition to pulmonary granuloma-forming activities, PIM2 was shown to recruit NKT cells into granulomas." (PMID 19290049, 2009).
hepatoblastoma (1 paper, 2018). Hepatoblastoma (HB) is a malignant hepatic tumor and is the most common pediatric liver cancer. "The expression of PIM kinases (PIM1, PIM2, and PIM3) was evaluated in the long-term passaged human hepatoblastoma cell line, HuH6, and the human hepatoblastoma PDX cell line, COA67, by immunoblotting." (PMID 29854306, 2018). "We preliminarily showed that knockdown of PIM1 or PIM2 did not affect hepatoblastoma cell proliferation." (PMID 29854306, 2018).
liver cirrhosis (1 paper, 2020). "It will be interesting to study the role of PIM2 in the progression of liver cirrhosis on transgenic mouse in the future." (PMID 32641749, 2020). "Apart from the oncogenic function of PIM2 in HCC, we found that the expression level of PIM2 correlates with severity of liver cirrhosis in HCC patients." (PMID 32641749, 2020). "More importantly, we found the expression level of PIM2 increased with the progression of liver cirrhosis, and PIM kinase inhibitor AZD1208 treatment could effectively attenuate HCC cells’ tumorigenic ability both in vitro and in vivo." (PMID 32641749, 2020). "Interestingly, we found that compared with non-cirrhotic HCC patients, those with liver cirrhosis had a lower average ΔCt value of PIM2, which indicated a higher expression level of PIM2 in cirrhotic HCC patients." (PMID 32641749, 2020).
medullary carcinoma (1 paper, 2021). "In radiation-induced medullary carcinoma in 4W rats, the expression of Cdkn2a and Cxcr4 increased, whereas that of seven autophagy regulatory genes (Dapk1, Eif2ak3, Gaa, Hgs, Mapkl4, Mapt, and Pim2) and five autophagy machinery components (Atg4b, Atg5, Gabarapl2, Rab24, and Wipi1) decreased." (PMID 34580369, 2021).
myelodysplastic syndrome (1 paper, 2021). A clonal hematopoietic disorder characterized by dysplasia and ineffective hematopoiesis in one or more of the hematopoietic cell lines. "Recent studies have shown that in myelodysplastic syndromes (MDS), AML patients had high expression of PIM2 in CD34+ cells derived from bone marrow." (PMID 33854618, 2021).
ovarian tumors (1 paper, 2017). "We also found that PIM1 and PIM2 are overexpressed in a subset of human female breast, endometrial and ovarian tumors and that this overexpression correlated with clear inflammatory features and stem cell markers." (PMID 28938604, 2017). "Analysis of human breast, endometrial or ovarian tumors from public databases revealed a variable subset of tumors overexpressing PIM1 or PIM2." (PMID 28938604, 2017). "Therefore, we tested whether PIM1 and PIM2 expression is correlated with stem markers in human female breast, uterine and ovarian tumors." (PMID 28938604, 2017).
Sézary Syndrome (1 paper, 2014). "Furthermore, PIM1 and, again, especially PIM2, but not PIM3 expression was increased in a panel of 8 PTCL cell lines and primary tumoral T cells from 5 Sézary Syndrome patients relative to normal T cells from 3 healthy donors." (PMID 25386922, 2014).
T-cell leukemia (1 paper, 2014). A malignant disease of the T-lymphocytes in the bone marrow, thymus, and/or blood. "FACS analysis of four PIM1/MYC mice and one mouse from PIM2, PIM3, and BCLxl cohorts demonstrates only myeloid cell (GR-1 and CD11b) markers, indicating a myeloid, not T-cell leukemia." (PMID 25238262, 2014).